PCNA (proliferating cell nuclear antigen)
Diseases named in the same sentence as PCNA in open-access papers (continued):
Sharing a sentence is not in itself a finding about the gene and the disease.
tumor (continued). "Furthermore, the expression of PCNA and Ki-67 in tumor lysates was further supported by Western blotting, indicating BD could dramatically inhibit the proliferation of tumor cells." (PMID 29311937, 2017). "In addition, tumor implants dissected at 6-weeks post-implantation demonstrated reduced Ccl5 levels, increased apoptosis (cleaved caspase-3 expression), and reduced cell proliferation (PCNA expression) in the Ccl5 KD groups." (PMID 28380429, 2017). "Therefore, in addition to sanitizing oxidized nucleotides, upregulated MTH2 expression in CRC tissues may enhance PCNA stability to promote cell proliferation and tumor growth." (PMID 29285286, 2017). "Moreover, hematoxylin and eosin and immunohistochemistry showed that proliferating cell nuclear antigen levels in tumor tissues of the U937-MEG3-OE group exhibited decreased positivity for proliferating cell nuclear antigen than in those of the U937-CTRL group." (PMID 28400619, 2017). "Thus, highly replicative tumor cells showed strong nuclear PCNA foci." (PMID 28832631, 2017). "In a DMBA-induced skin hyperplasia assay in ‘Sensitivity to Carcinogenesis’ (SENCAR) mice, both topical and oral SWT inhibited DMBA-induced epidermal hyperplasia, expression of the proliferation marker Proliferating cell nuclear antigen (PCNA), and H-ras mutations." (PMID 28335476, 2017). "H&E staining and immunohistochemistry of tumor tissues confirmed this treatment could result in the best effect to induce tumor necrosis and reduction of expression of the tumor cell proliferating marker (PCNA)." (PMID 29135959, 2017). "The results showed that PCNA-positive cells (dark brown) in the tumor xenograft tissues from chaetocin-treated mice were markedly decreased, which suggested that chaetocin treatment could effectively suppress cell proliferation in tumor xenografts." (PMID 28419143, 2017). "Immunohistochemical analysis shows Compound A to increase levels of cleaved caspase-3 and decrease the levels of the proliferation marker, PCNA compared to the control tumors, suggesting that this treatment is able to effectively induce apoptosis and reduce cell proliferation in the tumor tissue." (PMID 28439094, 2017). "In agreement with this, our immunohistochemical results show that not only PCNA but also CD31 (endothelial marker) were markedly suppressed in honokiol-treated xenograft tumor tissues, indicating that honokiol may be regarded as a useful antiangiogenic agent for the treatment of OSCC." (PMID 27012679, 2016). "Immunohistochemical analysis of the tumor regions revealed low-intensity p85 expression in the p42-AV and p42 (183–394 and 280–394 aa)-AV injection groups, than that of control or p48-AV injected group, with less frequent expression of proliferating cell nuclear antigen (PCNA)." (PMID 27464702, 2016). "Thus, abnormal expression of PCNA and cyclin D1 could induce a dysfunctional cell cycle and, in turn, promote angiogenesis and tumor growth." (PMID 27492854, 2016). "The IHC results indicated that the expressionof PCNA was significantly decreased in the μsPEFs treated groupcompared to the sham and control groups (both p < 0.001), suggesting that the μsPEFs treatment inhibittumor cells proliferation after tumor ablation in vivo." (PMID 25928327, 2015). "In addition, the immunohistochemical analysis of tumor tissue showed significant decrease in expression of proliferation proteins PCNA and MKI67, and also increased expression of apoptotic proteins p-RB, p21, and p-ERK1/2 indicating the pro-apoptotic role of the regimen." (PMID 26301084, 2015). "Finally, tumor cells may induce expression of exosomal proliferating cell nuclear antigen (PCNA) when physically contacted by NKp44 expressing NK cells to inhibit NK cell effector function." (PMID 25699048, 2015).
tumor (continued). "To determine whether the regression in tumor growth by purified crocetinic acid is due to inhibition of proliferation, apoptotic cell death or both, we first determined the expression of proliferating cell nuclear antigen (PCNA) as well as that of phosphorylation of EGFR and Akt." (PMID 26317547, 2015). "In addition, Western blot analysis show that PCNA protein expression downregulate, and Caspase 3 protein expression upregulate, indicating that tumor cells’ proliferation was significantly inhibited by combination treatment with oxaliplatin or Exendin-4, but apoptosis rate increased." (PMID 24351817, 2013). "The reversely proportional correlation identified between HSP27 expression and PCNA based on the double staining results may indicate that HSP27 only has an incomplete inhibition effect on the expression of PCNA in tumor cells and certain other unknown pathways may be involved." (PMID 23599795, 2013). "Although we found an association of PCNA+ TAMs with M1-type but not M2-type gene expression, these genes could be from the TAMs, tumor cells, or other cells." (PMID 24205370, 2013). "In addition, anti-Ly6G antibody treatment reduced NE mRNA expression and PCNA+ tumor cells." (PMID 23272179, 2012). "Finally, we evaluated tumor cell proliferation using PCNA staining." (PMID 20497582, 2010). "It was found that KIAA0101 could bind to PCNA and a putative tumor suppressor." (PMID 16646990, 2006). "Classical tumour markers, including MMP2, MMP9, PCNA, and Ki67, had significantly decreased mRNA expression in the siRNA group." (PMID 41284374, 2025). "Furthermore, the upregulation of PCNA and MKI67 genes, associated with tumor cell proliferation, was observed in the C2 subtype, indicating that patients with short-term survival may exhibit aberrant dysprogression of cell cycles and increased tumor cell proliferation." (PMID 40362506, 2025). "The observed reduction of tumor growth by NPTM was consistent with histological and PCNA IHC findings, indicating TM significantly reduced PCNA-expressing cell numbers." (PMID 41035776, 2025). "EZH2, PCNA, and BIRC5 were predominantly expressed in epithelial clusters, supporting their tumor-intrinsic roles." (PMID 40678068, 2025). "We further performed IHC on these tumours, and the ACADS-OE tumours had decreased staining intensities of Ki-67, PCNA, and CD34 when compared to NC tumours." (PMID 39800718, 2025). "An elevated PCNA expression reflects increased proliferative activity in aggressive tumor phenotypes, while high TNF-α levels contribute to an inflammatory tumor microenvironment that facilitates cancer cell invasion and metastasis." (PMID 40430573, 2025). "In the eight experimental groups, SERPINA1 knockdown reversed ITGB3 overexpression-induced effects, normalizing PCNA/Vimentin elevation and E-cadherin suppression (P < 0.05), establishing ITGB3 as the primary effector of SERPINA1-mediated tumor progression." (PMID 41467954, 2025). "The GA + Gem group showed minimal proliferating cell nuclear antigen (PCNA) marker staining (27%) compared to control (95%), GA (86%), and Gem (42%) treatments in vivo, indicating that tumor cell proliferation was suppressed by the GA + Gem group." (PMID 40900835, 2025). "Current research has developed small molecule inhibitors targeting PCNA, such as TX-101, PCNA-I1S, and T2AA, demonstrating significant anti-tumor activity in various cancer models." (PMID 41024300, 2025). "The assessment of tumor growth was then evaluated through both immunofluorescence analysis and real‐time PCR targeting PCNA (proliferating cell nuclear antigen)." (PMID 40545912, 2025).
tumor (continued). "Initially, to analyze the proliferative state and tumor characteristics of the 3D HCC model, the expression levels of PCNA (proliferating cell nuclear antigen), Ki-67 (Kiel 67 antigen), and AFP (Alpha-Fetoprotein) were quantified." (PMID 41008923, 2025). "In vivo, co-injection of CD70-expressing fibroblasts with cSCC cells accelerates tumor growth, whereas CD70 knockdown impairs tumor progression and reduces PCNA, IL6, and MCP3 expression, confirming its functional relevance in the tumor microenvironment." (PMID 41510255, 2025). "The expression of PCNA was significantly higher in HCC tissues compared to normal liver tissues and its expression levels increased with the progression of tumor stages." (PMID 40313621, 2025). "Notably, in the DMBA + skimmianine treatment group, the tumor burden appeared reduced in approximately 49% of the animals, as evidenced by partial preservation of the mammary gland architecture, fewer malignant clusters, and attenuated PCNA and TNF-α immunoreactivity (p = 0.191)." (PMID 40430573, 2025). "The evaluation of the antitumoral effects of AuNR‐ECFCs was assessed also in the tumor masses with a double immunohistochemical analysis for CD31, highlighted with DAB staining (brown), and PCNA, highlighted with RED staining." (PMID 40545912, 2025). "In this study, although there seemed to be a trend of larger volume and increased tumor volume, MVD, and expression of VEGF, Ki67, and PCNA in VX2 tumors under the background of fatty liver, these differences have not yet reached statistical significance." (PMID 40994954, 2025). "Regarding tumor proliferation, OXP represents partial retention of proliferative capacity, as indicated by moderate levels of PCNA expression." (PMID 40940848, 2025). "Histological analysis further confirmed that tumor sizes were markedly smaller in the NUAK2-CR cohort, with notably fewer Ki67 and PCNA-expressing cells." (PMID 40770117, 2025). "Molecular insights from in silico analyses further indicated that PCNA inhibition may affect cell cycle regulatory mechanisms, while TNF-α suppression may influence TLR-associated signaling pathways, suggesting a possible modulatory role of skimmianine in tumor progression." (PMID 40430573, 2025). "The preclinical inhibitor ML323 selectively targets USP1–UAF1, increases PCNA-Ub and FANCD2-Ub, amplifies replication stress, promotes apoptosis, and sensitizes tumor cells to cisplatin, suggesting a route to overcome platinum resistance." (PMID 41190241, 2025). "C1GALT1 was upregulated in several GI and GU cancers, correlating with poor survival and elevated expression of proliferation markers like MKI67, PCNA, and MCM2–7, suggesting a role in tumor growth." (PMID 40548474, 2025). "DLL3 expression was significantly higher in UCEC tissues compared to adjacent non-tumor tissues, Besides, IHC results also showed higher PCNA and Ki67 expression in patients in the DLL3 high expression group or tumor group." (PMID 40066092, 2025). "In protein expression level of tumor tissues, MEL-dKLA treatment increased the expression of E-cadherin while reducing the levels of Fibronectin, PCNA, and TGF-β compared to control groups." (PMID 41019043, 2025). "We systematically evaluate emerging candidates including PCNA inhibitors, HDAC inhibitors, and carbonic anhydrase inhibitors, focusing on their ability to modulate the tumor microenvironment and enhance immunotherapy responses." (PMID 41024300, 2025).
tumor (continued). "The DNA repair pathway plays a role in tumor dissemination, and molecules such as poly (ADP-ribose) polymerase 1 (PARP1), NME/NM23 nucleoside diphosphate kinase 1 (NME1) and proliferating cell nuclear antigen (PCNA) are highly expressed in metastatic lesions." (PMID 39780291, 2025). "These measurements demonstrated that thieno[2,3-b]pyridines potently block cell proliferation, evidenced by consistent decreases in PCNA expression across all explants treated with DJ160, including tumour samples resistant to enzalutamide." (PMID 40641632, 2025). "Subsequently, we examined PCNA and ki67 expression in RCC tumor tissues using immunohistochemical analysis." (PMID 40458080, 2025). "Further research showed that knockdown of PCNA significantly repressed the expression of PCNA and PARP1 in HepG2 xenograft tumor tissues." (PMID 40313621, 2025). "IHC staining for proliferating cell nuclear antigen (PCNA) confirmed that combining lovastatin and radiotherapy markedly inhibited tumor cell proliferation in vivo." (PMID 40355720, 2025). "We further assessed cell proliferation by examining Ki67 and PCNA expression, and evaluated cell migration through E-CAD and N-CAD levels in tumor tissues." (PMID 40740234, 2025). "Subcutaneous xenograft nude mouse model showed that DDX42 significantly promoted tumour growth as compared to the control group and lifted the expression of GRB2, KI‐67 and PCNA in vivo." (PMID 40831000, 2025). "PCNA, BCL2, TRAF2, XIAP and FKBP5 expression levels in whole RNAs extracted by 36 tumor tissue samples were quantified as relative expression, using expression from healthy donor PBMCs as a reference sample (=1)." (PMID 41256864, 2025). "VPA–NaDCA and TMZ reduced the invasion of U87 and T98G tumors, as well as the expression of PCNA and EZH2 in the tumor." (PMID 40725030, 2025). "Taken together, these data suggest that levels between tumor and adjacent non-tumor tissue of TERRA and PCNA can influence CRC patient survival." (PMID 39222177, 2025). "Decreased PCNA and increased cleaved caspase 3 levels were found in ZNF652 overexpression tumor tissues." (PMID 39500884, 2024). "Based on these findings, 11 pairs of tumor and adjacent tissues before RFA and after RFA were collected for assessing mRNA expression of APC, FAS, HGF, PCNA and EFCAB7." (PMID 39276379, 2024). "Histological staining of tumour sections from an early phase clinical trial, after treatment with HSV1716, revealed expression of PCNA positive cells." (PMID 39205238, 2024). "A xenograft model demonstrated the anti-tumor activity of CBD and the induction of cellular senescence through immunohistochemistry targeting PCNA, β-gal, and p21." (PMID 39850601, 2024). "Western blotting revealed lowered expression levels of PCNA, MMP2, MMP9, and VEGF, providing additional evidence for the anti-tumor efficacy of ZSTK474." (PMID 39466763, 2024). "Recent studies also reveal that MSC-Exo can upregulate proliferating cell nuclear antigen (PCNA), activate the ERK1/2 signaling pathway, and accelerate angiogenesis, thereby supporting tumor development." (PMID 39724442, 2024). "In vivo experiments demonstrated that ITGA5-EVs-148a significantly suppressed the tumor growth and the expression levels of ITGA5, PCNA, ACTA2, and FSP." (PMID 39099892, 2024). "Other studies revealed that SIN inhibited the proliferation of SK-Hep1 and induced apoptosis, decreasing PCNA, PI3K p85α, AKT1, BcL-2, and pro-caspase-3/-9 and increasing cleaved caspase-9/-3 in tumor tissue." (PMID 38276618, 2024).
tumor (continued). "Interestingly PCNA may also play a role in cells of the tumour microenvironment." (PMID 39205238, 2024). "PCNA staining was reduced in TKO tumors when compared to DKO tumors, indicating that Skp2 deletion suppresses tumor proliferation." (PMID 38355807, 2024). "The orthotopic tumors were then excised and subjected to IHC and TUNEL assays to determine the percentages of proliferating cell nuclear antigen (PCNA)‐positive and TUNEL‐positive cells for evaluation of tumor cell proliferation and apoptosis, respectively." (PMID 38417121, 2024). "IHC showed a Proliferating cell nuclear antigen (PCNA) index in cancer cells, and the α-SMA expression area in CAF cells was decreased when treated with Az in tumor tissues." (PMID 38715057, 2024). "In SCC-9 tumor cells, AC-AFPK-IsCT1 peptide treatment resulted in a significant decrease in the expression of the proliferation marker PCNA, with a reduction of 21.4 ± 0.4% compared to control cells." (PMID 39407463, 2024). "The examination of tumor tissue showed that CCDC80 and PCNA proteins expression in si-CCDC80 group was lower than si-NC group." (PMID 38872096, 2024). "We used HE staining to evaluate tumor morphology and IHC analysis to evaluate BZW2 expression, Ki67 expression and PCNA expression." (PMID 38424042, 2024). "The subcutaneous tumor group of TGF-β1 showed higher Ki-67 and PCNA expression levels than that of Vehicle group in mice." (PMID 38184549, 2024). "After 90 days, tumor tissues were harvested for IHC analysis, demonstrating a marked downregulation of EIF3B, PCNA and Ki-67 levels in the EIF3B knockdown group." (PMID 38687509, 2024). "RNH1 knockdown upregulated the expression of PCNA and MMP9, and RNH1 overexpression declined it, suggesting that RNH1 inhibited LUAD tumor formation in vivo." (PMID 38783241, 2024). "Down‐regulation of SRC‐1 decreased HCC cell proliferation and impaired tumour maintenance in HCC xenografts, and knockdown of SRC‐1 reduced protein levels of the proliferation marker proliferating cell nuclear antigen (PCNA) and the oncogene c‐Myc." (PMID 38506084, 2024). "The observed high immunoreactivity for both PCNA and CD3A markers within SCC tumor mass is in agreement with our bioinformatic predictions." (PMID 39428471, 2024). "RT-PCR analysis of xenograft tumor lysates revealed that the expression levels of E-cad, Slug, ITGB8, ITGB1, PCNA, and BAX showed a similar pattern to those observed in vitro, and Western blot results also confirmed these findings." (PMID 39459033, 2024). "MET was enriched in proliferating tumor cells featuring high levels of markers of cell cycle progression such as cyclins b1 and b2 (CCNB1, CCNB2), proliferating-cell nuclear antigen (PCNA) and Ki67 (MKI67) and likely define yet another subset of MBM." (PMID 38386085, 2024). "It has been confirmed that tumor proliferation-related markers MKI67 and PCNA (proliferating cell nuclear antigen) are closely related to the differentiation, invasion, and metastasis of many tumors." (PMID 38402311, 2024). "Silencing ILF2 expression in PDAC inhibited cell cycle progression and decreased the expression of cell cycle regulators like cyclin E1 (CCNE) and proliferating cell nuclear antigen (PCNA), hindering tumor cell proliferation." (PMID 39735599, 2024). "Our present data supported the function of RNU12 in inhabiting GC tumor progression through suppressing the cell growth, migration, invasion, as well as the proliferative ability expression with CCND1, PCNA, N-cadherin, E-cadherin, Vimentin and BCL-2." (PMID 37160927, 2023). "Subgroup 1 exhibited elevated expression levels of cell cycle genes PCNA and MKI67, as well as the tumor stem cell marker CD44." (PMID 37608794, 2023).